BCL6 (BCL6 transcription repressor)
Diseases named in the same sentence as BCL6 in open-access papers (continued):
Sharing a sentence is not in itself a finding about the gene and the disease.
tuberculosis (1 paper, 2021). A chronic, recurrent infection caused by the bacterium Mycobacterium tuberculosis. "Overall, our study suggests that IL-7 and transcriptional factors Id3 and Bcl6 help the TB subunit vaccine to induce long-term immune memory, which contributes to providing immune protection against M. tuberculosis infection." (PMID 33562631, 2021). "Therefore, IL-7 and transcription factors Id3 and Bcl6 could help the TB subunit vaccine to induce long-term immune memory, which would provide long-term immune protection against M. tuberculosis infection." (PMID 33562631, 2021).
viral pneumonia (1 paper, 2016). Inflammation of the lung parenchyma that is caused by a viral infection. "The failure to remove the Bcl6 regulator, however, impedes the antiviral signaling and exaggerates viral pneumonia in mice." (PMID 26728228, 2016). "Notably, this proinflammatory property of Bcl6 appeared to be congruent with the observed effect of the Bcl6 blocking peptide, RI-BPI, which potentially alleviated the inflammatory pathology in mouse model of viral pneumonia." (PMID 26728228, 2016).
ZIKV infection (1 paper, 2019). "The adoptive transfer of sera collected on 14 dpi also demonstrated that immune sera from Bcl6 intact mice had better protection against weight loss and mortality caused by ZIKV infection." (PMID 31455769, 2019).
tumor (382 papers, 2004 to 2026). "To study the function of BCL6 in the tumor immune response, we analyzed tumor growth in various conditionally deficient BCL6 models." (PMID 41145211, 2026). "In comparing tumor types, mutations in BCL6 were found to be significantly enriched in metastatic samples." (PMID 41597409, 2026). "To investigate the association between Bcl6 expression and the outcomes of tumor samples, we took advantage of the GEPIA database, which can be used to analyze the RNA-sequencing data of tumor samples under the TCGA and GTEx projects." (PMID 41145211, 2026). "The enrichment of BCL6 mutations in metastatic samples, though based on small numbers, suggests a potential link to advanced tumor progression." (PMID 41597409, 2026). "We found that BCL6 deficiency in activated CD8 T cells enhanced tumor repression in multiple mouse models." (PMID 41145211, 2026). "Our analysis is limited to the 3-wk tumor-bearing period, preventing an assessment of longer term effects of BCL6 deficiency or pharmacological repression." (PMID 41145211, 2026). "BCL6 expression was associated with advanced tumor stage and a higher incidence of metastasis to the lymph nodes, omentum, and mesentery." (PMID 40777995, 2025). "miR-127 is one of the tumor suppressor genes located on chromosome 14q32.31, encodes a protein that suppresses Bcl-6." (PMID 38685086, 2024). "Collectively, from these data, we can conclude that Bcl6 knockout turned the immune cells deficient “cold” tumor into cytotoxic immune cells rich “hot” tumor." (PMID 38956432, 2024). "The test results showed that the tumor-specific mutations in this sample were as follows: BCL6, TNFAIP3, PRDM1, CREBBP, DTX1, and FOXO1." (PMID 37884941, 2023). "Clinicopathological data analysis of GC patients from our hospital indicated that the low expression of BCL6 was closely associated with later pN stage, larger tumor size, and poor survival outcomes." (PMID 37060074, 2023). "Next-generation sequencing revealed six tumor-specific mutated genes (IGH/BCL6, TNFAIP3, PRDM1, CREBBP, DTX1, and FOXO1)." (PMID 37884941, 2023). "It has been shown that GCs in tumor-associated TLSs exhibit weaker proliferative activity and decreased Ki67 and BCL6 expression compared to GCs in secondary lymphoid organs." (PMID 36776859, 2023). "Overexpression of BCL6 is associated with tumor immune surveillance and drug resistance during the process of chemotherapy and radiotherapy." (PMID 36531232, 2022). "Loss of Bcl6 accordingly skews macrophages to glycolytic catabolism and pro-inflammatory phenotype, which tends to cause metabolic competition between TAMs and tumor cells, placing macrophages at proliferation and survival disadvantage in expanding tumors." (PMID 36542153, 2022). "By contrast, TLR4−/− macrophages remained Bcl6lowLy6Chigh phenotype during the whole period of tumorigenesis, implying that induction of TLR4 and subsequent Bcl6 were associated with macrophage tumor-promoting activity." (PMID 36542153, 2022). "CREBBP is one of the most frequently mutated genes in DLBCL and acts as a tumor suppressor of germinal center-derived lymphomagenesis by promoting transcription, counteracting the inhibition of B-cell lymphoma 6 (BCL6)." (PMID 33593440, 2021). "Here again, we confirmed that the ileal mRNAs encoding Gata3, Bcl6, Rorc, and Tbx21 were increased in tumor bearers at day 10 of implantation compared to naive counterparts." (PMID 33262469, 2021). "Transferring CD62L+ tumor-infiltrating cells with Bcl6 deficiency resulted in a significant reduction in both frequencies and cell numbers in the recipient mice." (PMID 32845913, 2020).
tumor (continued). "Consistent with FACS data, the deficiency of Bcl6 resulted in reduced expression of Foxp3 in Treg cells in tumor model." (PMID 32477338, 2020). "At D16 post tumor implantation, using flow cytometry analysis, we found that the deficiency of Bcl6 results in an impairment of Treg cells, evidenced by the decreased proportion and absolute number of Foxp3+CD4+ T cells." (PMID 32477338, 2020). "Further, retention of expression of BCL6 in cell lines underlies the importance of BCL6 in tumor cells." (PMID 32320427, 2020). "In this article, we reported that the deletion of Bcl6 specifically in Treg cells led to stunted tumor growth, which was caused by impaired Treg cell responses." (PMID 32477338, 2020). "Tumor cells are usually strongly Bcl-2 positive, and Bcl-6 is also expressed in most cases with evidence of Bcl-6 gene mutations." (PMID 25035687, 2014). "Our results suggest that the BCL-6 pathway is disrupted as inflamed tissue transforms into tumor, with the possibility that loss of BCL-6 expression leads to increased cancer invasion via increased MMP-9 expression." (PMID 23737761, 2013). "On immunohistochemistry tumor cells showed positive staining for B-cell-associated antigens (CD 20, CD 10), B cell lymphoma 6 protein (Bcl6), paired box gene 5(PAX 5), surface IgM and IgD as well as monoclonal Kappa light chains." (PMID 22866970, 2012). "In this project, we found that the deficiency of Bcl6 in Treg cells impaired the lineage stability and suppressive function of Treg cells, thus promoting the priming and activation of anti-tumor immune responses which led to significantly delayed malignant transformation in 4NQO-induced HNSCC model." (PMID 40290124, 2025). "Finally, BCL6 is able to induce a stem-like memory program in tumor-associated macrophages to promote long-lasting pro-tumor immunity." (PMID 39456751, 2024). "Further, we used xenograft mouse model to show that Bcl6 in cancer cell has mild effect on tumor growth in immune-deficient mice, but could prominently increase tumor progression in immune-competent mice, suggesting a role of Bcl6 in cancer immune evasion." (PMID 38956432, 2024). "As depicted above, differentiation of SMMs was a coherent process coupling enhanced mitochondrial metabolism with restrained glycolytic catabolism, we thus also explored the mechanism underlying Bcl6-mediated regulation of glycolytic pathway in tumor-conditioned macrophages." (PMID 36542153, 2022). "Tumor suppressor genes Kmt2d and Dusp4 showed similar loss of interactivity of their promoters with putative H3K27Ac rich loci in Smc3/Bcl6 tumors." (PMID 34621263, 2021). "Interestingly, we found that only 8 genes were mutated in at least one Bcl6 tumor, while 119 of them were mutated in at least one Smc3/Bcl6 tumor." (PMID 34621263, 2021). "Finally, Bcl6 is a gene involved in cell adhesion, negative regulation of the immune response, and inflammation and myeloid-specific deficiency of Bcl6 has been shown to decrease tumor growth and metastasis." (PMID 34743736, 2021). "Since ZBTB16, ZBTB28, and BCL6 were associated with tumor metastasis, replenishment Transwell assays were used to confirm our hypothesis." (PMID 32517789, 2020). "Given that the deficiency of Bcl6 in Treg cells resulted in repressed tumor growth in mouse models, we further checked whether Bcl6 expression could be exploited as an indicator for the clinical prognosis of human cancer patients." (PMID 32477338, 2020). "Consistent with the detection of Bcl‐6 at tumour‐associated TLSs, Bcl6 expression was increased in gp130F/F antrum tissue suggesting the presence of germinal centre B cells or Tfh cells, and was also highly expressed in the tumours of gp130F/F mice." (PMID 29417587, 2018). "It is silenced in tumor cells, which causes the overexpression of the proto-oncogene bcl-6." (PMID 20346162, 2010).
tumor (continued). "These preclinical experiments suggest that HDAC3-specific inhibition may be an effective therapy for GCB lymphomas, particularly those with CREBBP-mutations, by reducing the dominance of BCL6 on transcription programs and improving both terminal differentiation and immunogenicity of tumor cells." (PMID 35071240, 2021). "We also show that introducing a powerful small molecular drug treatment to suppress BCL6 works even after the tumor grows to nearly 200 mm3 volume." (PMID 41145211, 2026). "Here, we show that genetic or pharmacological suppression of BCL6 in activated CD8 cells promotes tumor control." (PMID 41145211, 2026). "Conditional deletion of Bcl6 in activated CD8 T cells or pharmacological inhibition of BCL6 in mice represses tumor growth." (PMID 41145211, 2026). "Collectively, these data demonstrate that the BCL6 inhibitor Fx1 controlled tumor progression in a T cell–dependent manner." (PMID 41145211, 2026). "Western blotting assays confirmed BCL6 expression in tumor cell lines, leading to the identification of the small molecule compound DZ-865B." (PMID 41799511, 2026). "Targeting Bcl6 repressed the tumor growth of murine HNSCC which further enhanced the therapeutic efficacy of ICB therapy, indicating that Bcl6 inhibition represents a promising strategy for clinical HNSCC treatment." (PMID 40290124, 2025). "B‐Cell Lymphoma 6 (BCL6) is a nuclear transcriptional repressor that can regulate tumor cell proliferation and apoptosis through gene translocation and deregulated expression." (PMID 41438489, 2025). "Biological function tests showed that BCL6 contributes to tumor cell proliferation, invasion, and migration, and plays an important role in the progression of HGSOC in vivo." (PMID 40777995, 2025). "One case showed variable staining of CD20 and CD79a in 90% of tumour cells, and was positive for BCL6 (weak) and MUM1 (strong)." (PMID 41047873, 2025). "The germinal center B-cell-like (GCB) subtype was defined as the identification of CD10+ or CD10–/BCL6+/MUM-1– tumor cells." (PMID 40694139, 2025). "The novelty of this study lies in the first demonstration that the natural product‐derived molecule FLLL31 induces tumor cell apoptosis by targeting the FOXO4/BCL6 axis." (PMID 41438489, 2025). "IHC analysis of the respective tumor samples showed efficient suppression of PLAAT4 upon overexpression of BCL6, while the expression of p-AKT was significantly increased." (PMID 40777995, 2025). "By inhibiting monocyte activation, Bcl6 expression and glycolytic reprogramming, the formation of tumor‐promoting macrophages is blocked and their functions are reversed." (PMID 41211186, 2025). "We next decided to use mice with the tamoxifen-inducible CD4+ T-cell-specific deletion of Bcl-6 (Bcl6fl/flCD4CreER) to define the impact of Bcl-6 deletion on the early and late stage of anti-tumor CD4+ T-cell response to M002 treatment." (PMID 39885128, 2025). "The sustained increase of Bcl-6 to T-bet secondary to the deletion of T-bet in CD4+ T cells was deleterious to anti-tumor responses, and reduced Bcl-6 expression at the early stage of treatment only produced some survival benefit." (PMID 39885128, 2025). "Immunostaining showed that the tumor cells were positive for CD20 and BCL-2, and that a minor component of the tumor cells was undeniably BCL-6 positive." (PMID 40772219, 2025). "In vivo, we established a subcutaneous transplantation tumor model and abdominal metastasis model in nude mice to verify the role of BCL6 and PLAAT4 in HGSOC progression." (PMID 40777995, 2025). "We then asked what is the contribution of the stage-specific expression of Bcl-6 relative to T-bet to the anti-tumor CD4+ T-cell response to M002 treatment." (PMID 39885128, 2025).
tumor (continued). "Among these, the top three TFs—NFIC, HOXB2, and BCL6—demonstrated notably high expression in tumor cells." (PMID 40190189, 2025). "The abundance of Bcl6+CD11b+F4/80+Ly6C− SMMs in tumor tissues correlates with advanced tumor stage, increased metastasis, and poor overall survival in patients with colorectal cancer, breast cancer, and glioblastoma." (PMID 41211186, 2025). "Bcl6 inhibitor FX1 significantly delayed the tumor growth of HNSCC which further enhanced the anti-tumor efficacy of PD-1/PD-L1 ICB." (PMID 40290124, 2025). "Preclinical studies showed that BCL6 inhibition halted BCL6-positive tumor growth in mice, but also suppressed GC formation." (PMID 41246349, 2025). "Compared with patients with other FIGO stages of HGSOC, more patients with FIGO stage III/IV HGSOC had high BCL6 expression in tumor cells." (PMID 40777995, 2025). "Continuous measurement of tumor weight revealed that xenografts derived from sg-BCL6 cells grew much slower than those derived from sg-NC cells." (PMID 40777995, 2025). "Many BCL6 inhibitors that selectively kill tumor cells with high expression of BCL6 by blocking the interaction of BCL6 with SMRT, NCOR, and BCOR have been reported." (PMID 40821118, 2025). "The results showed that resveratrol similarly reactivated the BCL6 target genes expression in these tumor cells." (PMID 39815148, 2025). "Given Bcl-6+ hTregs’ complex and dual role in tumor immunity, further investigation into Bcl-6+ hTregs is crucial to understanding their impact on antibody responses and potential therapeutic strategies in cancer treatment." (PMID 41041322, 2025). "To ask at which stage the tumor infiltrating T cell infiltration and activation has been affected by Bcl6, we used flow cytometry to analyze CD45+ immune cells and T cells infiltrating kinetics on day 3, day 7 and day 14 post-surgery." (PMID 38956432, 2024). "We have demonstrated that Bcl6 knockout tumor has more T cell infiltration and the infiltrating T cell activation was also upregulated after Bcl6 knockout." (PMID 38956432, 2024). "WK369 improved the tumor response and enhanced the sensitivity of OV cisplatin-resistant cell lines to cisplatin, and down-regulated BCL6 expression." (PMID 38169532, 2024). "Our results were consistent with the CCLE database, which further revealed that BCL6 has tumor type-specific expression in OV and potentially affects the proliferation and metastasis of OV." (PMID 38169532, 2024). "Tumor cells were positive for cluster of differentiate (CD) 20 and B-cell lymphoma 6 protein (BCL-6)." (PMID 38974400, 2024). "By quantify the T cell subpopulation distribution for WT and Bcl6 KO groups, we found that about 80% WT group derived T cells located in T other population, which express much lower level of tumor cytotoxic genes." (PMID 38956432, 2024). "Distinct from its other roles in cancer cells, BCL6 separately influences tumor immunity in a variety of ways." (PMID 39456751, 2024). "For example, BCL6 acts as a transcriptional regulator that represses tumor suppressors thereby favoring cell proliferation and survival." (PMID 38248118, 2024). "The tumor image, tumor area and total liver weight in nude mice also implied a trend that BCL6 knockout slightly decreased HCC progression, while overexpression of Bcl6 upregulated HCC growth in nude mice." (PMID 38956432, 2024). "CXCR5 + BCL6+ Tfh cells were rare in the “Tumor-Adj” and “Tumor-Dis” sites of the tumor-bearing testis and in the contralateral testis." (PMID 38649788, 2024). "Tumors from mice treated with FX-1 also displayed reduced cell proliferation and metastasis, suggesting that targeting BCL6 reduces this tumor growth mainly via induction of cell cycle arrest, which is consistent with the previous findings." (PMID 38485719, 2024).